EGFR (epidermal growth factor receptor)
Diseases named in the same sentence as EGFR in open-access papers (continued):
Sharing a sentence is not in itself a finding about the gene and the disease.
tumor (continued). "Similar immune signature was previously reported in EGFR mutation-positive non-small-cell lung cancer (NSCLC), in which, elevated PD-L1 in EGFR mutant tumor was consider to be an indicator of better overall response rate to PD-1 inhibitors." (PMID 31801484, 2019). "Studies in APCmin/+ mice models have revealed a novel EGFR-independent oncogenic signal of EGF in the tumor microenvironment." (PMID 31370270, 2019). "Here, the authors show AURKB activation to be associated with resistance in EGFR mutant lung cancer cells, and that AURKB is a therapeutic target in resistant tumours that lack the p.T790M or other acquired mutations." (PMID 31000705, 2019). "In a phase III trial (KEYNOTE-024) comparing pembrolizumab with platinum-doublet chemotherapy in chemo-naïve patients whose tumor was positive for PD-L1 ≥ 50%, patients who had EGFR or ALK alterations were excluded." (PMID 31049758, 2019). "Although RICTOR aberrations did not affect survival in the entire TCGA cohort, in both PIK3CA amplified and EGFR amplified HNSCC tumor subsets, there is a trend toward a shorter time to relapse in cases with RICTOR aberrations versus in those without." (PMID 31393061, 2019). "EGFR promotes cell proliferation and angiogenesis and inhibits apoptosis as well as the escape of tumor cells from the immune response." (PMID 30863440, 2019). "Tumor uptake of [111In]In-DOTA-cetuximab uptake strongly correlated with the adjusted EGFR band density (r = 0.893, p < 0.005)." (PMID 31651282, 2019). "For instance, combination treatment with the SMOi saridegib and the EGFR inhibitor cetuximab abrogates tumor growth and delays tumor recurrence in mouse xenograft models derived from metastatic head and neck squamous cell carcinoma." (PMID 31244888, 2019). "On the other hand, the induction of HSP70 surface exposure and its release by gefitinib-treated tumor cells point to additional immune-modulatory effects of the EGFR TKI." (PMID 32082304, 2019). "TKIs are small molecular agents targeting EGFR mutations that have revolutionized the treatment of NSCLC, leading to improved survival in patients with advanced or metastatic EGFR-mutant tumor." (PMID 30736438, 2019). "EGFR signaling activates a pathway that promotes tumor proliferation, migration, stromal invasion, neovascularization, and resistance to apoptosis." (PMID 30915273, 2019). "In the actual tumor-targeted conjugate 4, the thiol analog of 1 (i.e., 2) is connected to the side chain of a Cys residue added to the N-terminus of the epidermal growth factor receptor (EGFR)-binding peptide GE11." (PMID 30841526, 2019). "In the context of metastatic CRC, CMS appears to associate with survival in clinical trials of patients with wild-type KRAS tumours, treated with anti-EGFR or VEGF inhibitors." (PMID 31775679, 2019). "Tumor-status of the organoids was confirmed using DNA sequencing (which included targeted sequencing of EGFR), and organoids were further characterized using RNA sequencing and functional drug screens." (PMID 31694307, 2019). "EGFR signaling pathway is a traditional carcinogenic signaling pathway, which plays a critical role in tumorigenesis and tumor progression." (PMID 31368612, 2019). "Alternatively, there was no significant influence on the PC-9RPD-L1+ tumours, indicating immune depression tumour microenvironment (TME) on xenografts in vivo after acquired EGFR-TKIs resistance." (PMID 31747941, 2019). "Ablation of EGFR was most evident in tumor cells edited with sgRNA3, confirmed with T7E1 assay and Western blot." (PMID 30710055, 2019). "EGFR overexpression correlates with increased tumor growth rate, invasiveness and decreased survival, which makes it a favorable target for TRNT of GBM." (PMID 31374991, 2019). "The tumor promoting effects of the GPER operate through the EGFR transactivation and related signaling pathways." (PMID 30646517, 2019).
tumor (continued). "EGFR is a tyrosine kinase involving in activation of various cellular processes such as cell proliferation, differentiation, and tumor progression." (PMID 31470870, 2019). "WtEGFR also plays a critical oncogenic role in GBM, contributing to tumor cell invasion, and heterogeneous co-expression of wild type and mutant EGFR contributes to drug resistance in GBM." (PMID 30267146, 2019). "Among the remaining cases, the median time from tumor diagnosis to EGFR status confirmation was seven days (range: 0–84 days), with median times of seven days (range: 0–84 days) for ARMS and nine days (range: 0–42 days) for NGS." (PMID 31144459, 2019). "The elevated EGFR expression can promote the proliferation, angiogenesis, adhesion, invasion, and metastasis of tumor cells in multiple solid tumors and inhibit the apoptosis of tumor cells." (PMID 33817143, 2019). "When formulated with Th1-inducing adjuvants such as poly I/C or CpG, EGFR-specific cytotoxic T lymphocytes were activated which conferred antitumor immunity in mouse tumor models." (PMID 31749795, 2019). "Tumor genotyping was performed in 2316 Chinese NSCLC cases with targeted next generation sequencing (NGS) covering the whole exons of EGFR gene." (PMID 31208370, 2019). "In this scenario, the purpose of the current study was to modify genetically anti-tumor CD8+ cells to express EGFR to take advantage of the proliferative effect that EGFR ligands produced in the tumor microenvironment." (PMID 31921216, 2019). "KRAS and EGFR mutations are usually mutually exclusive but when they coexist, mainly in tumours under EGFR-TKIs treatment, KRAS mutations can confer resistance to EGFR inhibitors." (PMID 31795465, 2019). "Next, we investigated the efficacy of the combination of JQ1 and EGFR inhibitor in inhibiting HCC tumor growth in vivo." (PMID 30770740, 2019). "Cetuximab is an IgG1 monoclonal antibody against EGFR that can specifically bind to EGFR on various tumor cells and inhibit the binding of other ligands, thereby suppressing tumor growth and progression." (PMID 31684985, 2019). "As a proof of concept, we implemented ectopic expression of carbonic anhydrase IX (CA IX) and epidermal growth factor receptor (EGFR) in the plasma membrane of the SKOV3 tumor cell line." (PMID 30755643, 2019). "Other variants detected in this tumor, such as those inFGFR3,PDGFRA,KDR (c.1416A>T),CSF1R,EGFR,RET,HRAS,PIK3CA,FLT3 (c.1310-3T>C), andSMAD4, are benign." (PMID 32612806, 2019). "In an assessment of circulating tumor DNA (ctDNA) RET alterations in patients with cancer, 15 of 126 NSCLC patients had co-occurring EGFR mutation and 5 had developed resistance to prior EGFR TKI." (PMID 30915273, 2019). "The relationships of EGFR expression with clinicopathological characteristics and tumor recurrence status were analyzed." (PMID 31798535, 2019). "We first analyzed the expression of EGFR and their ligands in a panel of tumor cell lines as well as tumor biopsies obtained from mice previously inoculated with the tumor cell lines." (PMID 31921216, 2019). "Recent studies propose as a target for colorectal cancer EGFR (overexpressed in 60–80% of aggressive tumors) or CAE as chimeric antigen receptors allow T-cells to recognize tumor cells and quickly destroy them." (PMID 31303863, 2019). "Loss of EGFR overexpression on tumor cells observed in subcutaneous PDX and PDOX indicated EGFR inactivation in the PDX model for this particular tumor." (PMID 31732509, 2019). "Another nodal protein is EGFR, an epidermal growth factor receptor that plays an important role in the proliferation of tumor cells." (PMID 31523389, 2019). "EGCG also can suppress tumor metastasis through the regulation of related signaling pathways, such as the EGFR signaling pathway." (PMID 30857144, 2019). "In HCC, m6A acts as a tumor suppressor through YTHDF2-directed degradation of EGFR by binding the m6A site in the 3′ UTR of this mRNA." (PMID 31801551, 2019).
tumor (continued). "Experimental evidences from in vitro models, mouse xenografts and analysis of patient outcomes showed that VGF expression is associated with resistance to EGFR inhibitors and further induces epithelial-mesenchymal transition (EMT) and tumor cell dissemination." (PMID 31682594, 2019). "Thirdly, in our study, the association between DepOR and PFS was conducted only in patients with tumor shrinkage due to the limited number of patients with progressed disease upon EGFR-TKI." (PMID 31602263, 2019). "We then collected MPE samples from three patients with WT tumor in chemotherapy treatment (P29), untreated EGFR19Del tumor (P9), and EGFRL858R tumor that had developed resistance to EGFR targeted therapy (P3), respectively." (PMID 31451693, 2019). "To explore the mechanism by which apigenin regulated Noxa expression and synergized with ABT-263 to inhibit EGFRm tumor cells, we analyzed the phosphorylation status of EGFR and its downstream signalling pathways, including MAPK, PI3K-AKT and STAT3." (PMID 31367332, 2019). "Survival analysis revealed that overexpression of some oncogenes, such as EGFR, CDK6 or CDK4 were associated with poorer prognosis tumours." (PMID 31703248, 2019). "Preclinical and clinical studies have revealed a highly complex relationship between tumor biology and the efficacy of the anti-EGFR therapy." (PMID 31370270, 2019). "We examined the expression of EGFR and EGFR ligands using Real-time PCR in murine tumor cell lines and confirmed the broad expression of EGFR in tumors from different origin." (PMID 31921216, 2019). "EGFR plays crucial roles in epithelial malignancies, including tumor growth, invasion, and metastasis, through stimulation of downstream signaling cascades, such as ERK or AKT pathways." (PMID 31159758, 2019). "In this study, we revealed that miR-27a inhibits cell proliferation and invasion of cSCC, and suppresses the activation of NF-κB pathway through directly targeting EGFR, indicating that miR-27a plays a tumor suppressive role in cSCC." (PMID 32039029, 2019). "Our data suggests that EGFR antibodies paradoxically sustain MAPK signaling downstream of oncogenic RAS thereby driving proliferation of RAS mutant tumors or tumor subclones." (PMID 32039027, 2019). "Our previous work suggests that EGFR inhibition activates the interleukin-1 (IL-1) pathway via tumor release of IL-1 alpha (IL-1α), although the clinical implications of activating this pathway are unclear in the context of cetuximab therapy." (PMID 30890189, 2019). "We monitored wing discs for morphology, Cut expression, and pMAD in EGFR-Pcn tumor discs, and EGFR-Pcn tumor discs that also express BtlDN." (PMID 31568500, 2019). "EGFR is involved in pathways related to the tumor microenvironment, tumor cell metabolism, and controls cell survival mechanisms such as proliferation, hypoxia resistance, DNA damage repair and apoptosis." (PMID 31192138, 2019). "In all cases, EGFR protein levels detected on tumor cells were higher than those detected on matched normal organoids." (PMID 31694307, 2019). "Combination strategies with ERK1/2 pathway inhibitors and PD-L1/PD-1 inhibitors are considered to suppress PD-L1 expression in tumor cells to restore EGFR-TKI sensitivity in resistant cells." (PMID 31652644, 2019). "Using hFcαRI transgenic mice, IgA anti-EGFR antibodies were proven to mediate tumor cell killing in vivo." (PMID 31616408, 2019). "In the EGFR-Pcn tumor discs that also express BtlDN, characteristics of tumor morphology, size, pattern of Dpp signaling, and distribution of myoblasts were suppressed." (PMID 31568500, 2019). "Next, freshly explanted tumor samples and healthy tissue samples were briefly incubated with EGFR-FITC-SiO2-NPs in vitro, fixed, processed for paraffin sectioning and stained with DAPI." (PMID 31561451, 2019).
tumor (continued). "EGCG can inhibit the binding of EGFR to its receptor by inducing EGFR autophosphorylation, and inhibit EGFR internalization, EGFR signal transduction, and tumor cell proliferation and angiogenesis." (PMID 31058847, 2019). "De novo activating mutations occurring on the intracellular tyrosine kinase activity domain of EGFR can drive tumour growth." (PMID 30612556, 2019). "Recently, EGFR has been used as an anti-tumor target due to its relationship with tumor progression." (PMID 30821275, 2019). "Assessment of EGFR mutations is necessary in NSCLC patients to guide the use of EGFR-TKIs, and the gold standard is tumor tissue analysis." (PMID 30809319, 2019). "This case underlines the potential advantage of performing liquid biopsy at the time of tumor recurrence as compared to tissue analysis of the primary tumor for a better clinical prediction on the efficacy of anti-EGFR therapies." (PMID 31597339, 2019). "To monitor Bnl signaling in the EGFR-Pcn tumor model, we examined a Bnl reporter that expresses mCherry:CAAX in Bnl-expressing cells." (PMID 31568500, 2019). "Seven out of 9 patients received EGFR-TKIs before nivolumab and tumor tissues were obtained from these 7 patients after failure of EGFR-TKI treatment." (PMID 30978241, 2019). "Our study confirmed recent reports suggesting that EGFR-mutant tumours carrying additional driver alterations have a reduced sensitivity to EGFR TKIs." (PMID 30857358, 2019). "Disrupting the Golgi apparatus via inhibition of ADP ribosylation factor 1 (ARF-1) exerts anti-tumor activity against EGFR-activated tumor cells." (PMID 30899432, 2019). "The RAS induces angiogenesis and tumor proliferation by promoting vascular endothelial growth factor (VEGF) or epidermal growth factor receptor (EGFR) expression." (PMID 31139216, 2019). "Strong correlations were found between [111In]In-DOTA-cetuximab tumor uptake and EGFR expression level (r = 0.893), and between [64Cu]Cu-DOTA-cetuximab tumor uptake with EGFR expression level (r = 0.915)." (PMID 31651282, 2019). "The most common variant of EGFR is EGFRvIII, which results from a consistent and tumor-specific in-frame deletion of exons 2–7 of the EGFR gene." (PMID 30601871, 2019). "This is reminiscent of the upregulation of aerobic glycolysis in Hipk, EGFR or PDGF/VEGF-induced tumours in the Drosophila wing disc." (PMID 31513013, 2019). "By flow cytometric detection, EGFR+ cancer cells isolated from the smallest tumor (21 mg) expressed FRα, while EGFR+ cancer cells isolated from the two larger tumors (90 and 363 mg) had completely lost their FRα expression." (PMID 30941303, 2019). "Lastly, we discuss the potential strategies aiming to enhance the favorable effects in the tumor microenvironment to overcome resistance to EGFR-based therapies." (PMID 31370270, 2019). "At the meantime, epithelial tumor cells are more sensitive to EGFR inhibitors than tumor cells that acquired mesenchymal characteristics." (PMID 31138318, 2019). "In tumor colon cell lines, hydroxytyrosol reduced cell proliferation and tumor growth through the inhibition of epidermal growth factor receptor expression." (PMID 30897691, 2019).
tumor (continued). "The upregulation of the epidermal growth factor receptor (EGFR) into tumour cells can intensify its signalling and promote both abnormal rates of cell proliferation and cell survival." (PMID 31703248, 2019). "Several studies have investigated the relationship between PD-L1 expression on tumour cells and outcomes in EGFR-mutant patients treated with EGFR-TKIs, although the conclusions were contradictory." (PMID 31331328, 2019). "In patient-derived xenograft models, afatinib inhibited tumor growth in three cases with EGFR overexpression, EGFR amplification or HER2 amplification, respectively." (PMID 31557260, 2019). "At disease progression, the patients had rebiopsy and his tumor was found to had EGFR A763_Y764insFQEA and EGFR T790 M." (PMID 31208370, 2019). "Of note, patient accrual in these two trials was restricted to those with EGFR gene amplification in archival tumour specimens, with an expectation of their better response to PF-002998049." (PMID 30644426, 2019). "Among the most frequently detected CNAs, EGFR amplifications were accounted in 15/34 (44.1%) of the tumor samples from primary disease." (PMID 30894200, 2019). "AXL positivity in tumor tissue after the development of EGFR‐TKI resistance was 50% (5/10) for T790M‐positive specimens and 50% (4/8) for T790M‐negative specimens." (PMID 31419057, 2019). "Remarkably, tumor cells pretreated with anti-EGFR TKIs showed increased sensitivity towards NK cell-mediated antibody-dependent cellular cytotoxicity (ADCC)." (PMID 31546690, 2019). "Because of tumor spatiotemporal heterogeneity, NSCLC patients harbor EGFR mutations will have different drug response and clinical benefit treated with EGFR-tyrosine kinase inhibitors (TKIs)." (PMID 31555581, 2019). "Therapeutically, Wnt1-EarlyEx tumors showed a dynamic reduction in tumor volume when treated with an EGFR inhibitor." (PMID 31213486, 2019). "Abnormal expression of EGFR regulates tumor cell proliferation, migration, differentiation, and homeostasis." (PMID 31122294, 2019). "In recent studies of NSCLC, liquid biopsy was shown to detect driver gene mutations, such as EGFR and anaplastic lymphoma kinase (ALK) mutation, and tumor mutational burden." (PMID 31652678, 2019). "It is known that p.T790M mutation is only one of the existing resistant mechanisms developed by the tumor following to EGFR TKI treatment." (PMID 31860648, 2019). "This study is the first to document the mechanism by which 4.1B inhibits tumor cell proliferation by binding to the JM segment of EGFR." (PMID 31492173, 2019). "This study showed that four epidermal growth factor receptor tyrosine kinase inhibitors (EGFR TKIs) (gefitinib, erlotinib, lapatinib, and afatinib) were transported from tumor cells as substrates of ABCG2." (PMID 31340525, 2019). "In the EGFR-Pcn tumor model, Dpp signals from the genetically altered epithelial cells to drive myoblast expansion." (PMID 31568500, 2019). "High level of EGFR enhanced proliferation, promote tumor growth leading to poor prognosis and resistant to radiotherapy." (PMID 31692905, 2019). "Aptamers, small nucleic acids used in treatment, can disrupt EGFR/β3 integrin interaction to inhibit tumor growth." (PMID 31109009, 2019). "Therefore, the testing for plasma sensitizing EGFR mutation may serve as internal control that informs the likelihood of falsely negative T790M results and concomitantly, provide an indirect proof for circulating tumor derived DNA in the plasma." (PMID 31029076, 2019). "We have previously shown, consistent with others, that cancer exosomes contain the EGFR ligands, including AREG, suggesting that the EGFR system contributes to the exosome-mediated communication within the tumor microenvironment." (PMID 30621731, 2019).